IL1R1 (interleukin 1 receptor type 1)
Diseases named in the same sentence as IL1R1 in open-access papers (continued):
Sharing a sentence is not in itself a finding about the gene and the disease.
epilepsy (continued). "Interestingly, while in hippocampus both COX2 and IL-1r1 levels correlated with the epilepsy-predictive MRI signal change after eFSE, in amygdala the correlation was with IL-1r1 mRNA levels only." (PMID 26730400, 2015). "Overexpression of miR-636 inhibiting IL1R1 expression could markedly downregulate the TLR4 signalling pathway not just in CF but also in other diseases, such as epilepsy, in which inactivation of the IL1R1/TLR4 pathway is implicated." (PMID 31803183, 2019). "In addition, increased proinflammatory cytokines were found in the serum and CSF in patients with epilepsy, whereas the analysis of human brain specimens from drug-refractory epileptic patients showed strong activation of the IL-1b/IL-1R1 system in brain resident cells, such as in glia and neurons." (PMID 20863362, 2010). "In this review, we mainly focus on the IL-1β/IL-1R1/IL-1Ra pathway and HMGB1/TLR4 pathway, in which recent advances in knowledge have been made for epilepsy." (PMID 41155637, 2025). "Towards clinical translation, we carefully reviewed existing substances and drugs targeting the IL-1β/IL-1R1/IL-1Ra pathway and HMGB1/TLR4 pathway and their effects on epilepsy models and patients." (PMID 41155637, 2025). "IL-1R1 and TLR4 are expressed in astrocytes and BBB ECs and have been shown to be upregulated in clinical and experimental studies of epilepsy." (PMID 39206290, 2024). "The neuroimmune inflammatory response mediated by IL-1β/IL-1R1 and HMGB1/TLR4 signaling pathways plays an important role in the pathogenesis of epilepsy." (PMID 37305762, 2023). "Epilepsy-induced sleep disturbances were absent in the IL-1R1 KO mice, indicating the importance of IL-1 signals." (PMID 27875989, 2016). "The increase of NREM sleep after ZT13 kindling stimulus in the wildtype mice, but not in the IL-1R1 KO mice revealing the importance of IL-1 receptors in epilepsy-induced sleep alterations." (PMID 27875989, 2016). "While this elevation was not significant on group levels for IL1-R1 and COX2, it occurred in ∼40% of rats, which is consistent with previous work and the proportion of rats developing epilepsy." (PMID 31685676, 2019).
asthma (27 papers, 2010 to 2025). "The results revealed that IL1-R1 was also found to be associated with asthma in different databases, with an increased risk of asthma associated with elevated IL1-R1 levels (OR = 1.22; 95% CI 1.09–1.37, p = 6.71 × 10−4)." (PMID 39806440, 2025). "Asthma is an allergic disease, and we found that IL1R1 and Layilin are both associated with allergic diseases, whereas ECM1 is related to atopic dermatitis." (PMID 39806440, 2025). "Genome‐wide association study (GWAS) indicated that the gene polymorphisms of IL‐33/IL‐1R1 pathway showed association with development of wheeze and asthma in early childhood." (PMID 37102668, 2023). "Our integrative analysis revealed that asthma risk is causally affected by the levels of IL1R1, ECM1, and PDLIM4." (PMID 37809092, 2023). "Several genome wide association studies have found SNPs in genes encoding IL-33 or its receptor ST2 (IL1R1) to be risk factors for eosinophilic asthma, early childhood onset asthma, and severe forms of the asthma Airway biopsies of asthmatics have higher IL-33 mRNA expression than healthy subjects." (PMID 31490928, 2019). "Using this framework, one study nominated IL1R1(Interleukin 1 Receptor Type 1), ECM1(Extracellular Matrix Protein 1), and PDLIM4 (PDZ and LIM Domain Protein 4) as causal asthma targets, with additional signals implicating ECM1 in neuro-immune pathways." (PMID 41459491, 2025). "Our study demonstrated a causal relationship between genetic determinants, including IL1R1, IL7R, ECM1, CD200R1, ADAM19, IL-6 sRa, and Layilin (LAYN) protein levels, and asthma." (PMID 39806440, 2025). "Specifically, in plasma, we found that an increase of one standard deviation in IL1R1 and ECM1 was associated with an increased risk of asthma, while an increase in ADAM19 was found to be protective." (PMID 37809092, 2023). "We reported the association of polymorphisms within the IL1 receptors type I (IL1R1) and type II (IL1R2) gene loci with asthma and atopy in the French Canadian Saguenay–Lac-Saint-Jean (SLSJ) asthma study." (PMID 26246860, 2015). "In the present study, we measured DNA methylation at the IL1R1 and IL1R2 gene loci and assessed for associations with asthma-related phenotypes and gene expressions." (PMID 26246860, 2015). "The critical role of IL-1/IL-1R1 in the development of allergic Th2 responses in both mild and more severe asthma has been studied." (PMID 20671916, 2010). "Additionally, using the same analysis method in the FinnGen database, we found that IL1-R1, ADAM19, and IL7R were associated with asthma risk, further demonstrating the stability of the results obtained in this study." (PMID 39806440, 2025). "In addition, ERBB3, IL1R1, IL1RL2, IL6R, LRRC32, STAT6, and TNFRSF6B have been strongly linked to allergic diseases, such as asthma and rhinitis." (PMID 38773393, 2024). "Our study demonstrates a causal relationship between genetically determined IL1R1, ECM1, and PDLIM4 plasma protein levels and asthma and, additionally, a causal relationship between ECM1 protein levels in brain tissue representing neurogenic inflammation and asthma." (PMID 37809092, 2023). "The target proteins of current asthma medications were found to interact with IL1R1." (PMID 37809092, 2023). "The study identified three potential drug targets for asthma, including IL1R1, ECM1, and PDLIM4." (PMID 37809092, 2023). "Additionally, IL1R1 and PDLIM4 were found to be associated with asthma in two other large asthma GWAS datasets, further supporting the reliability of the potential drug targets identified in this study." (PMID 37809092, 2023). "In this study, we hypothesized that DNA-Me in the promoters of IL1R1 and IL1R2 is associated with asthma and/or atopy." (PMID 26246860, 2015). "Together, IL1R1 might be a potential therapeutic target for asthma." (PMID 37809092, 2023).
asthma (continued). "The importance of IL-1β in asthma is highlighted by the observations that IL-1β is elevated in BAL fluid and sputum; it is associated with nocturnal asthma; and the expression of its receptor (IL-1R1) is positively correlated to stress markers in asthmatic patients." (PMID 30906226, 2019). "A causal relationship exists between genetically determined protein levels of IL1R1, IL7R, ECM1, CD200R1, ADAM19, IL-6 sRa, and Layilin (LAYN) and asthma." (PMID 39806440, 2025). "However, mice with an IL-1R1 deficiency on radioresistant lung epithelial cells fail to raise a TH2 immune response and do not develop house dust mite-induced asthma, whereas caspase 8-mediated IL-1 activity promotes TH2 immunity and contributes to the development of asthma pathogenesis." (PMID 33584721, 2020). "In contrast, in a model of more severe asthma, eosinophilic inflammation, antibody responses, and CD4+ T cell priming in lymph nodes are comparable between IL-1R1 (−/−) and wild-type mice." (PMID 20671916, 2010). "Currently, there are no studies on combined therapy targeting IL1-R1 and IL-7R, providing new insights for our research on targeted asthma medications." (PMID 39806440, 2025). "However, OS biomarkers NO2−, lipid peroxide, protein sulfhydrils, and inflammatory biomarkers TNFα, IL-4, IL-37, IL-1β, IL-1RL1, IL-1R1, NLRP3, and TGF-β1 showed positive association with asthma in nonsmokers, but not in smokers." (PMID 37367073, 2023).
Arthritis (25 papers, 2005 to 2025). Inflammation of a joint. "Additionally, patients with single nucleotide polymorphisms (SNPs) in Myd88, Il1a, and Il1r1 genes have an increased risk of osteomyelitis and inflammatory joint disorders, further underscoring the importance of these immune pathways in skeletal homeostasis." (PMID 30978245, 2019). "Fas-deficient mice developed arthritis that was less severe, probably through a reduced IL-1R1/Toll-like receptor-4 signaling that might contribute to a decreased expression of other cytokines, chemokines and matrix metalloproteinases potentially regulated by this pathway." (PMID 15987490, 2005). "In agreement with this idea, it has been shown that the TLR4 ligand lipopolysachariden (LPS) is able to restore the development of K/BxN serum transfer arthritis in Il1r1−/− mice, which were protected from the development of pathology in the absence of LPS." (PMID 34412663, 2021). "Accordingly, the incidence of arthritis, dermatitis and conjunctivitis were reduced in Il1r1−/−TTP−/− mice as compared to TTP−/− animals." (PMID 32733464, 2020). "Imatinib suppressed such MSU crystal-induced ankle swelling and leukocyte infiltration in IL-1R1-/- mice, indicating that the drug can inhibit IL-1-independent pathways contributing to arthritis in this acute gout model." (PMID 28982129, 2017). "Importantly, treatment of IL-1R1-/- mice with imatinib suppressed both the ankle swelling and the leukocyte infiltration associated with exposure to this high concentration of crystals, indicating that the drug can inhibit IL-1-independent pathways contributing to arthritis in this acute gout model." (PMID 28982129, 2017). "Furthermore, although suggested by the efficacy of the anti-IL-1R1 antibody, complete target coverage of the antibody within the joint over the whole duration of the arthritis experiment seems difficult to verify." (PMID 23324173, 2013). "In contrast, the same level of arthritis incidence was observed at the age of 6-7 weeks in TTP−/− mice and at the age of 25 weeks in Il1r1−/−TTP−/− mice." (PMID 32733464, 2020). "Treatment of the mice with the anti-ST2 antibody before and during development of arthritis did not reduce disease severity in two independent experiments, while blocking of the type 1 IL-1R with an isotype-matched anti-IL-1R1 blocking antibody essentially abrogated disease." (PMID 23324173, 2013).
atherosclerosis (25 papers, 2009 to 2025). A disease characterized by the build-up of fatty material and calcium deposition in the arterial wall resulting in partial or complete occlusion of the arterial lumen. "To confirm the causal association between IL-1R1 and EndMT in human unstable atherosclerosis, we first re-assessed the relative expression of active IL-1R1 and EndMT genes in macroscopically intact tissue vs. atheroma tissue from an online dataset (GSE43292)." (PMID 37539090, 2023). "Taking into account the important role of EndMT in progressive human atherosclerosis and IL-1R1 signaling roles, in this study, we directly assessed IL-1R1 expression and linked it to EndMT in human atherosclerotic plaques." (PMID 37539090, 2023). "Having shown that IL-1R1 expression is locally increased in human unstable atherosclerosis and that is associated with EndMT, we first asked if IL-1R1 is expressed under areas of d-flow, and if that is associated with EndMT." (PMID 37539090, 2023). "Our first observations on the association between IL-1R1 and Snail1 in human unstable atherosclerosis where the lesions exhibit more complex and advanced phenotype than that to the mice." (PMID 37539090, 2023). "We show that central nervous system inflammatory pathology is associated with the development of atherosclerosis in high-fat diet–fed ApoE−/− mice and, through genetic deletion of IL-1R1 or neutralization of IL-1β, provide evidence that this is mediated by IL-1." (PMID 23130147, 2012). "Our study is the first to demonstrate an enhanced IL-1R1 expression in human atherosclerosis stages IV and V, and that is predominantly within the endothelium." (PMID 37539090, 2023). "Our study should aid in developing future strategies for targeting the IL-1R1 within the endothelium to limit atherosclerosis progression and maintain lesion stability." (PMID 37539090, 2023). "In mice, either global or myeloid specific deletion of IL-1R1 reduces atherosclerosis, whereas cell specific deletion of IL-1R1 in vascular smooth muscle cells increases atherosclerosis and make lesions more unstable." (PMID 37539090, 2023). "Collectively, the data demonstrates that IL-1R1 is expressed predominantly in endothelial cells in stable advanced human atherosclerotic plaques, however, the expression of IL-1R1 is increased in EndMT in unstable human atherosclerosis." (PMID 37539090, 2023). "This changed not only with development of the ApoE−/−Fbn1C1039G+/− and Il1r1−/−ApoE−/− but also the tandem stenosis (TS) mouse model, which can mimic various stages of human atherosclerosis, including type VI lesion rupture." (PMID 32714944, 2020). "Therefore, the action of IL-1α may suffice to allow cell migration and compensatory remodeling when targeting IL-1β to reduce inflammation in atherosclerosis, avoiding the potentially adverse effects of abrogation of signaling by both isoforms noted in IL-1R1-deficient mice." (PMID 27032103, 2016). "One method involves the use of bone marrow transplants into constitutive IL-1R1-/- mice to establish a requirement of IL-1R1 signaling by bone-marrow derived cells for features of atherosclerosis." (PMID 26930558, 2016). "EndMT is a spectrum of phenotypic changes in ECs and whether inhibition of IL-1R1 mediated EndMT in atherosclerosis is yet to be investigated and future studies from our laboratory will focus on dissecting the downstream pathway(s) involved." (PMID 37539090, 2023). "To further explore whether the expression of IL-1R1 is altered by the advanced stages of atherosclerosis, we categorized the human progressive atherosclerotic plaques into two grades, either IV or V as per the AHA recommendations." (PMID 37539090, 2023). "As expected, in mice with an atherosclerosis phenotype, IL-1R1 expression is predominant in the atheroprone areas as assessed by immunofluorescence and no IL-1R1 staining was detected in the athero-protective area of the aortic arch." (PMID 37539090, 2023).
atherosclerosis (continued). "Interestingly, lesions that are very stable show predominant expression of IL-1R1 within the endothelium and hardly any Snail1 expression, suggesting that EndMT is not happening in the stable human atherosclerosis." (PMID 37539090, 2023).
autoimmune disease (23 papers, 2010 to 2025). A disorder resulting from loss of function or tissue destruction of an organ or multiple organs, arising from humoral or cellular immune responses of the individual to their own tissue constituents. "The biochemical basis by which IL-1 exerts pathogenic effects is still elusive, although IL-1R1 signaling has been linked to the differentiation of T helper (Th) 17 cells, which are essential for the development of autoimmune disease." (PMID 35163653, 2022). "In the current study, we evaluated the efficacy of topical administration of IL-1R1 antagonist (IL-1RA) anakinra in alleviating ocular surface damage resulting from aqueous-deficient dry eye in the setting of autoimmune disease." (PMID 24068863, 2013). "Although topical application of IL-1R1 antagonist is an effective therapy in mouse models of corneal injury and desiccating stress, the therapeutic potential for treating aqueous tear deficiency in autoimmune disease remains unknown." (PMID 24068863, 2013). "IL-1R1 signaling plays a key role in Th17 cell differentiation and the development of autoimmune diseases." (PMID 39211643, 2024). "Pathogenic Th17 cells, with higher expression of Il17, Csf2, Il23r, and Il1r1, play a pivotal role in the pathogenesis of autoimmune disorders." (PMID 37716986, 2023). "Comparison of rules for each disease revealed that TLR3, TLR5, IL18, IL18R1, and IL1R1 genes occurred in rules for all studied diseases, showing good discriminant power among studied autoimmune diseases as visualized by the Andrews curves." (PMID 31396542, 2019). "Recently, it was reported that IL-1 receptor type 1 (IL-1R1) is critical in the differentiation of Th17 cells, which mediates the progression of autoimmune diseases." (PMID 29692782, 2018). "Our studies were the first to establish local signaling via the IL-1/IL-1R1 pathway as a portal for KCS/SQM development in the setting of autoimmune disease." (PMID 24068863, 2013). "The authors highlighted that the therapeutic targeting of IL-1R1 may hold promise in Th17-related autoimmune disorders." (PMID 35163653, 2022). "An increase of IL-1R1 expression and IL-1 production has been reported in aged rodents, suggesting that CD4+ T cells from the animals are highly responsive to IL-1R1 stimulation and prepared to differentiate into Th17 cells, which is closely linked to autoimmune diseases." (PMID 26673738, 2015). "IL1RL2, IL6R, ERBB3, ICAM1, IL1R1, and GALK1 were also enriched in categories like immune system disease, autoimmune disease, skin disease, and disease of anatomical entity." (PMID 38773393, 2024).
melanoma (20 papers, 2011 to 2025). A malignant, usually aggressive tumor composed of atypical, neoplastic melanocytes. "With fibroblasts being the potential recipients of the IL-1 signal in the melanoma microenvironment, we wished to assess the effects of IL-1R1 activation in fibroblasts." (PMID 28450382, 2017). "In agreement with our findings in melanoma biopsies, we found that established melanoma cell lines express only very low levels of IL-1R1 if any, whereas human foreskin fibroblasts (HFFs) expressed high levels of IL-1R1." (PMID 28450382, 2017). "However, as it has been reported that tumor cell lines, including melanoma cell lines, can express IL-1R1, we can postulate that IL-1β, which is known to promote matrix metalloproteinase expression, could increase the production of sHLA-E by IL-1R1 expressing tumor cells." (PMID 21712991, 2011). "We show that blocking IL-1R1 signaling or CXCR2 signaling synergizes effectively with MEK inhibition in vivo, suggesting this as a means to delay the onset of resistance that presently too frequently occurs in melanoma patients." (PMID 28450382, 2017). "Importantly, IL-1R1 expression was not detectable in melanoma cells." (PMID 28450382, 2017). "In contrast to melanoma, in our orthotopic PDAC models, IL-1R1 blockade failed to enhance agonistic CD40 antibody efficacy." (PMID 40060615, 2025).